SAA1 (serum amyloid A1)
Diseases named in the same sentence as SAA1 in open-access papers (continued):
Sharing a sentence is not in itself a finding about the gene and the disease.
coronary artery disease (7 papers, 2019 to 2025). "The most enriched proteins in ICM are serum amyloid A1, lipopolysaccharide-binding protein, and activated protein C, which are biomarkers associated with coronary artery disease." (PMID 38259301, 2023). "Our observation of increased SAA1 in STEMI is consistent with previous reports where high levels of SAA1 can be predictive of coronary artery disease and cardiovascular outcome." (PMID 32671099, 2020). "SAA1 plays an active role in atherosclerosis and coronary artery disease (CAD)." (PMID 30737305, 2019). "SAA1 can displace apoA-I from HDL when concentrations of the acute phase protein are elevated, such as in coronary heart disease patients." (PMID 30842338, 2019). "In this regard, elevated SAA1 plasma levels have been recently suggested to accurately individuate the presence of acute coronary syndrome (ACS), correlating with the severity of coronary artery disease (CAD) in the studied patients." (PMID 33505588, 2021).
Alzheimer disease (6 papers, 2012 to 2025). A progressive, neurodegenerative disease characterized by loss of function and death of nerve cells in several areas of the brain leading to loss of cognitive function such as memory and language. "Other studies in humans showed that SAA1 was detected in senile plaques in Alzheimer’s disease tissue, predominantly localized to neuritic plaques." (PMID 34070533, 2021). "Established markers of Alzheimer’s disease and neurodegeneration, including TREM2, SAA1, CHIT1, CRP and PDGFRB demonstrated strong correlations (r > 0.8) in the comparison with SomaLogic measurements." (PMID 41250190, 2025).
Arthritis (6 papers, 2009 to 2025). Inflammation of a joint. "Here, we identified that Saa1, Saa2, and Saa3 expression in the liver, an extraarticular organ, were markedly increased in IL-1β–induced arthritis." (PMID 38426494, 2024). "Elimination of microbiota after the onset of arthritis resulted in suppression of intestinal SAA1, SAA2 and IL-22 expression and a specific reduction of LP Th17 cells accompanied with reduced Th17 cell abundance in joint-draining lymph nodes of the CIA mice." (PMID 29142301, 2017). "In NSG-RA mice, in vivo signs of arthritis as well as the expression of murine Saa1 and Cxcl13 in the joints increased upon challenge, whereas the development of histopathological alterations and the secretion of inflammatory plasma cytokines occurred spontaneously, without challenge." (PMID 40977310, 2025). "SAA1 overexpression in the liver accelerates progression of mBSA/IL-1β–induced arthritis." (PMID 38426494, 2024). "Notably, overexpression of Saa1 in the liver substantially increased IL-1β–induced arthritis." (PMID 38426494, 2024).
esophageal cancer (6 papers, 2022 to 2025). A primary or metastatic malignant neoplasm involving the esophagus. "In addition, a new subpopulation of epithelial cells have been identified in esophageal cancer, namely SAA1+ epithelial cells, that contribute to esophageal cancer distant metastasis by single cell profiling." (PMID 40248695, 2025). "Through the assessment of EMT levels in epithelial cells and the comprehensive analysis of key genes and pathways, we found a group of SAA1+ malignant epithelial cells in esophageal cancer that are highly invasive and play an important role in the distant metastasis of ESCC." (PMID 36605443, 2022). "Based on these results, we speculated that the increased SAA1 might be due to excessive inflammatory cytokines, which have previously been proven to be produced by cancer cells in patients with advanced esophageal carcinoma." (PMID 35610567, 2022).
gastric cancer (6 papers, 2022 to 2025). A primary or metastatic malignant neoplasm involving the stomach. "Elevated concentration of SAA1 is associated with occurrence, recurrence and survival of gastric cancer." (PMID 36505781, 2022). "SAA1 has been connected suppressing the microbial-induced inflammation and tissue damage, a protective action in gastric cancer, considering that it is often associated with infections, such as Helicobacter pylori infection." (PMID 35052827, 2022). "Given that some of the upregulated hub genes in our study, such as SAA1 and TNFRSF11B, are involved in inflammatory and immune-related pathways, targeting them with zoledronic acid may provide a repurposing opportunity to disrupt tumor-supportive signaling in H. pylori–associated gastric cancer." (PMID 40445003, 2025).
Hepatitis (6 papers, 2013 to 2026). Inflammation of the liver. "Thus, we further analyzed inflammation effectors and modulators, such as the cytokines shown before, to aggravate T cell-mediated hepatitis following SAA1 overexpression." (PMID 36423130, 2022). "In our data the SAA-1 and SAA-2 were indentified to increase with the highest degree, which is also supported that SAA has a high correlation with hepatitis." (PMID 23763817, 2013).
inflammatory bowel disease (6 papers, 2020 to 2025). A spectrum of small and large bowel inflammatory diseases of unknown etiology. "Interestingly serum amyloid A1 (Saa1) has been associated with a protective role in inflammatory bowel disease and is upregulated in the 9D1 treated animals." (PMID 36420263, 2022). "In a series of studies conducted by Littman and coworkers, Saa1/Saa2 was shown to play a pivotal role in Th17 immunity using mouse models of inflammatory bowel disease and the colonization of segmented filamentous bacteria (SFB)." (PMID 39940756, 2025). "SAA1 expression has been demonstrated as an important link between the mucosal microbial community, T cells, and the tissue environment in patients with inflammatory bowel disease." (PMID 35126370, 2021). "Recently, SAA1 has been found to play key roles in bacterial clearance, immune regulation, and tumor pathogenesis, and it was also identified as an important link between mucosal T cells, microbial communities, and their tissue environments in patients with inflammatory bowel disease." (PMID 31906950, 2020).
anemia (5 papers, 2014 to 2022). A reduction in the number of red blood cells, the amount of hemoglobin, and/or the volume of packed red blood cells. "As IL-6 is thought to be an important cause of the anemia of inflammation by inducing hepcidin expression, we used SAA-1 measurements as an indicator of IL-6 activity." (PMID 24681760, 2014). "Taken together with the increase in SAA-1 levels, these data point to a hepcidin-independent inflammatory mechanism for anemia." (PMID 24681760, 2014). "In order to evaluate the contribution of inflammation and hepcidin activity to the development of anemia in our cancer models, we measured the hepatic mRNA concentrations of SAA-1 and hepcidin." (PMID 24681760, 2014). "After a single intraperitoneal injection of heat-killed Brucella abortus, the mice developed a severe anemia with the characteristics of AI: increased SAA-1 and hepcidin, and iron restriction with increased tissue iron stores." (PMID 24681760, 2014). "In addition, SAA-1 levels were not elevated, confirming that these mice developed an iron-deficiency anemia rather than AI." (PMID 24681760, 2014). "At 18.5 weeks, ID8 mice had depressed liver hepcidin mRNA levels as compared to controls (ID8 0.20 vs. PBS 14.08, P = 0.013), as well as comparable SAA-1 levels to controls (P = 0.361), indicating that inflammation and hepcidin do not play a major role in the development of this anemia." (PMID 24681760, 2014).
breast tumors (5 papers, 2019 to 2025). "Syngeneic breast tumors were established in wild-type and SAA1/2-deficient (SAADKO) mice, with assessments of tumor volume, survival, inflammatory profiles, and tumor characteristics." (PMID 39336082, 2024). "However, it is also evident from our study that the expression of the interleukins is finely regulated by both knockout of SAA1/2 and autophagy inhibition in breast tumors." (PMID 36248994, 2022). "Further research is warranted to explore the mechanisms by which SAA1/2 influences tumor biology, particularly in different tissue contexts, and to determine whether other factors might compensate for the absence of SAA1/2 in maintaining the aggressive phenotype of breast tumors." (PMID 39336082, 2024). "The lack of significant differences in mitotic counts and the presence of grade 3 carcinomas in both groups suggest that the absence of SAA1/2 does not markedly alter the aggressive histopathological features of breast tumors in this model." (PMID 39336082, 2024). "We detected the expression of SAA1 in lymph node metastasis-negative and -positive breast tumor tissues by immunohistochemical staining, and found that SAA1 levels were much higher in breast tumor tissues with lymph node metastasis." (PMID 31390756, 2019). "The observed similarity in histological features between SAADKO and WT tumors implies that SAA1/2 may not play a pivotal role in modulating the histopathological grade or structure of breast tumors, contrary to its effects observed in other cancer models." (PMID 39336082, 2024).
endothelial dysfunction (5 papers, 2019 to 2026). In vascular diseases, endothelial dysfunction is a systemic pathological state of the endothelium (the inner lining of blood vessels) and can be broadly defined as an imbalance between vasodilating and vasoconstricting substances produced by (or acting on) the endothelium. "Another acute-phase protein that serves as a biomarker of endothelial dysfunction is serum amyloid A (SAA), a family of acute-phase apolipoproteins encoded by four genes—SAA1, SAA2, SAA3, and SAA4—and produced primarily by hepatocytes and macrophages." (PMID 41155389, 2025). "SAA1 also drives ROS production in endothelial cells and leads to endothelial dysfunction via inhibition of eNOS." (PMID 38698864, 2024). "In HFpEF, metabolic stress-induced SAA1 may contribute to endothelial dysfunction by directly or indirectly enhancing the expression of vascular adhesion molecules." (PMID 41313351, 2026). "Beyond promoting the expression of endothelial adhesion molecules, SAA1 may exacerbate endothelial dysfunction in HFpEF through its adverse effects on HDL functionality." (PMID 41313351, 2026).
nasopharyngeal carcinoma (5 papers, 2015 to 2022). A carcinoma arising from the nasopharyngeal epithelium. "In addition, a previous study demonstrated a close correlation between certain SAA1 allelic variants and nasopharyngeal carcinoma, some of which exhibited anti-angiogenic and tumor-suppressive activities." (PMID 35936690, 2022). "SAA1 protein expression is upregulated in many common cancers, including lung, ovarian, renal, uterine, and nasopharyngeal cancer." (PMID 25652121, 2015). "Interestingly, there are significant differences in SAA1 genotype ratios between nasopharyngeal carcinoma and GC." (PMID 35705840, 2022).
periodontitis (5 papers, 2016 to 2023). An acute or chronic inflammatory process that affects the tissues that surround and support the teeth. "Out of the 20 most upregulated genes in periodontitis tissues compared to controls, five were induced in DAC-treated GFs in our experiments (CSF3, GLDC, SAA1, SAA2, GDF15), highlighting the notion that DNMT inhibitors upregulate several genes that are associated with periodontitis pathology." (PMID 36776856, 2023). "Periodontitis and CKF show genetic cross-talk, which is supported by five hub genes, i.e., CCL5, FCGR3B, MMP-9, SAA1, and SELL." (PMID 37510279, 2023). "In conclusion, five hub cross-talk genes, i.e., CCL5, FCGR3B, MMP-9, SAA1, and SELL, could be involved in the interplay between periodontitis and CKF, whereby primarily inflammation, metabolic, and vascular issues appear to be of relevance." (PMID 37510279, 2023). "Furthermore, while the liver gene analyses indicated increased levels of Saa1 or Tnf was evident in mice with periodontitis it was not possible to detect these proteins in serum, which may be related to detection limits of the tests employed here." (PMID 34294791, 2021).
renal carcinoma (5 papers, 2021 to 2024). A carcinoma arising from the epithelium of the renal parenchyma or the renal pelvis. "SAA1 can be used as a biomarker to predict advanced renal cancer, and its knockdown can impair the ability of renal cancer cells to proliferate and metastasize." (PMID 38358909, 2024). "According to survival analysis of Human Protein Atlas, SAA1 is also a prognostic gene with high expression for unfavorable outcomes in renal cancer." (PMID 35565241, 2022).
Stroke (5 papers, 2015 to 2025). Sudden impairment of blood flow to a part of the brain due to occlusion or rupture of an artery to the brain. "The present study demonstrated that SAA1/2 is a promising predictor, at hospital admission, of stroke patients at risk of developing an infection." (PMID 28701906, 2017). "The results demonstrated that SAA1/2 is an efficient infection-risk prediction marker in stroke patients." (PMID 28701906, 2017). "If confirmed, SAA1/2 concentrations could be used to identify the patients most at risk of post-stroke infections and therefore implement treatments more rapidly, thus reducing mortality." (PMID 28701906, 2017). "SAA1 is a potential biological marker for early detection and prognosis assessment in individuals who have experienced a stroke." (PMID 40537921, 2025). "SAA1/2 has already been described as a potential marker of inflammation and infection in several pathological conditions, including stroke and subarachnoid hemorrhage." (PMID 28701906, 2017). "Some studies have reported that SAA1 can activate NOD‐like receptor thermal protein domain‐associated protein 3 in microglia within the brain, leading to the release of IL‐1 and subsequent promotion of neuroinflammatory responses following a stroke." (PMID 40537921, 2025). "After selecting SAA1/2 as the most promising protein, parallel reaction monitoring (PRM) and the enzyme-linked immunosorbent assays (ELISA) confirmed its ability to predict which patients were at risk of infection after a stroke." (PMID 28701906, 2017). "In a small cohort of stroke patients, we were able to demonstrate that the concentrations of SAA1/2 measured at hospital admission could be used to predict post-stroke infection." (PMID 28701906, 2017). "Therefore, as in stroke, an important inflammatory response is triggered after TBI that could be dramatically increased by the important rise of SAA1 serum levels." (PMID 34070533, 2021).
viral infection (5 papers, 2017 to 2025). "We demonstrate that iNKT cells promote the secretion of Saa1 and other acute-phase proteins in the early stage of viral infection in the liver." (PMID 29163475, 2017). "Among these proteins, CRP, SAA1, and SAA2 are described as common markers for inflammation and combined monitoring of CRP and serum amyloid A has previously been shown to increase specificity for monitoring viral infections." (PMID 39441646, 2024).
acne (4 papers, 2018 to 2026). An inflammatory process of the sebaceous glands which is characterized by comedones, nodules, papules and/or pustules on the skin. "Of these genes, serum amyloid A 1/2 (SAA1/2) was confirmed to be a suitable protein marker for in vivo activated sebocytes, underlining their immune-competence, which is structurally defined within sebaceous glands of acne and rosacea skin samples." (PMID 29927962, 2018). "SAA1 levels did not significantly correlate with acne severity (p = 0.052) or scar severity (p = 0.09)." (PMID 41814843, 2026). "Importantly in our in vivo studies, sebocytes also stained strongly positive for SAA1/2 suggesting that they may as well contribute to the levels of SAA1/2 in the local tissue environment and perhaps even in the serum, which calls for further studies to assess it in acne patients." (PMID 29927962, 2018). "Moreover, SAA1 has been found to increase also in keratinocytes in response to TLR2 activation, which was further augmented when glucocorticoids were used in combination, suggesting a possible contribution of SAA to (steroid-induced) acne." (PMID 29927962, 2018).
brain trauma (4 papers, 2015 to 2022). "SAA1 is an acute-phase, high-density lipoprotein secreted by the liver in response to infection and tissue injury; thus, its plasma levels are elevated following injury, inflammation, brain trauma, and cancer." (PMID 35756918, 2022). "The predictive value of serum SAA1 is better at 72 h than 24 h or 7 days after brain trauma." (PMID 34070533, 2021). "Injury, inflammation, and brain trauma can elevate the plasma levels of SAA1." (PMID 30867991, 2019). "In this study, hepatic levels were increased tenfold over the magnitude seen previously, raising the possibility of a greater specific role for SAA-1 following ischaemic brain injury, or, more likely, that the MCAO model produces a greater hepatic APR than direct central inflammatory challenge." (PMID 25994490, 2015).
carotid atherosclerosis (4 papers, 2010 to 2015). A thickening and loss of elasticity of the walls of carotid arteries that occur with formation of atherosclerotic plaques. "Many studies have demonstrated that rs12218 in the SAA1 gene was associated with carotid atherosclerosis and peripheral arterial disease." (PMID 23898911, 2013). "The mechanisms which may link SAA1/2 genetic polymorphisms to carotid atherosclerosis are largely unknown." (PMID 21103356, 2010).
diabetes (4 papers, 2016 to 2022). "Similarly, serum Amyloid A1 (SAA1), a top differential expression finding of RolDE, has been previously linked to diabetes and blood glucose levels in multiple studies." (PMID 36550114, 2022). "Expression of transcription factors (ANGPTL2, HP, LEP, SAA1, SAA2), genes related to inflammation (SAA1, LEP), diabetes (IGFBP5) and cancer risk (SAA2) were also elevated upon exposure to 5 nM PhIP.." (PMID 27547236, 2016). "However, we did find that PhIP induces changes in gene expression in various genes that are related to inflammation (SAA1, LEP), diabetes (IBP5) and cancer risk (SAA2)." (PMID 27547236, 2016).
liver cancer (4 papers, 2021 to 2025). An epithelial or non-epithelial malignant neoplasm that arises from the liver. "Macrophage recruitment and M2 polarization was also observed in the study of the “invasive zone” of liver cancer in which a subpopulation of damaged hepatocytes produces excessive SAA1 and SAA2 for local immunosuppression in human patients." (PMID 39940756, 2025). "SAA1 was highly expressed in liver cancer among various cancer categories." (PMID 37081987, 2023). "We also detected a clear upregulation of several liver cancer marker genes such as AFP, GPC3, SAA1, and VIL1 in transformed iHeps and in CMT + sgTP53 tumors compared to control fibroblasts; AFP was also found among the most enriched genes in both CMT + sgTP53- and CMT-transformed iHeps." (PMID 34302118, 2021).
lung adenocarcinoma (4 papers, 2014 to 2022). A carcinoma that arises from the lung and is characterized by the presence of malignant glandular epithelial cells. "Consistent with our dataset, there was a broad range of SAA1/2 expression levels in lung adenocarcinoma tumours, including many tumours with high SAA levels." (PMID 34203378, 2021). "Thus, plasma levels of SAA1 should be further studied in clinically relevant patient groups to investigate its true value as a biomarker for lung adenocarcinoma." (PMID 36232544, 2022). "When distinguishing lung adenocarcinoma and SqCC, the combination of CEA, CYFRA 21-1, NSE, and SAA1 has the highest sensitivity of 75.76%, a specificity of 70.97%, and an AUC value of 0.7605." (PMID 34439874, 2021). "In their turn, the pro-inflammatory cytokines, IL-1β, IL-6 and TNF-α, regulators of SAA1 and SAA2 genes, were also found to be increased in patients with lung adenocarcinoma." (PMID 28250368, 2014).